TIAM1 (TIAM Rac1 associated GEF 1)
Diseases named in the same sentence as TIAM1 in open-access papers (continued):
Sharing a sentence is not in itself a finding about the gene and the disease.
breast cancer (continued). "However when looking at clinical outcome for these patients, levels of TIAM-1 were significantly higher in tumour tissue from patients who died from breast cancer compared with those who survived p = 0.04." (PMID 18925966, 2008). "Additionally, we examined whether TIAM1 knockdown affects breast cancer cell HCC1806 growth by CCK‐8 assay." (PMID 39418072, 2024). "The observed changes in the SUM1315 breast cancer cells in our system are dependent on fibroblast-produced OPN, as OPN silencing or antibody-mediated inhibition abrogates the increased invasion, migration, and cancer stem cell properties induced by Tiam1-deficient fibroblasts." (PMID 26821678, 2016). "Thus, Tiam1 may act as a valuable molecular marker for breast cancer invasion, and play a key role in prognosis prediction." (PMID 27562113, 2016). "Thus, increased expression of Tiam1 might promote the malignant potential of breast cancer, and Tiam1 overexpression might be used as a potential predictive biomarker of poor prognosis in patients with breast cancer." (PMID 27562113, 2016). "Tiam1 expression correlated with clinicopathological parameters, suggesting that it may be a useful prognostic biomarker and potential therapeutic target for patients with breast cancer." (PMID 27562113, 2016). "Thus, in renal cell carcinoma, breast carcinoma, and gastric cancer, an inverse correlation has also been observed between Tiam1 expression and invasive potential, and Tiam1 expression in renal carcinoma cells inhibits migration by promoting E-cadherin-mediated adhesion." (PMID 20819206, 2010). "The statistical evidence in this study leads to the conclusion that the GEF TRIO may be particularly useful as a prognostic factor in breast cancer as its level is significantly increased in tumour tissue with Tiam-1 showing a significant increase in tumour tissue from patients with poor prognosis." (PMID 18925966, 2008). "In summary, our study demonstrated that YAP1 can upregulate TIAM1 expression by binding to its enhancer, which subsequently activates RAC1 and induces invadopodia formation in breast cancer." (PMID 35773411, 2022). "It inhibits mammary sphere formation of breast cancer cells NSC23766 is a specific inhibitor of a subset of Rac-specific GEFs, such as Tiam1 and Trio." (PMID 32392742, 2020). "These Tiam1/Rac1/MAPK pathway mechanisms promote tumorigenesis and metastasis in breast cancer, lung squamous cell carcinoma, pancreatic cancer, lung adenocarcinoma, and prostate cancer." (PMID 30171257, 2019). "miR-10b is significantly upregulated in metastatic breast cancer cells and initiates cell migration and invasion in murine xenograft model of breast cancer by targeting the HOXD10 gene along with E-cadherin and Tiam1." (PMID 30871273, 2019). "Univariate analysis demonstrated that breast cancer patients with high Tiam1 expression had significantly lower DFS and 10-year OS rates than those with low Tiam1 expression tumors." (PMID 27562113, 2016). "We found that breast cancer patients with high Tiam1 expression had lower DFS and 10-year OS (P = 0.003, respectively) rates than those with low Tiam1 expression." (PMID 27562113, 2016). "Conversely, OPN expression is significantly increased in fibroblasts associated with invasive breast cancers compared to fibroblasts associated with DCIS, suggesting the relevance of fibroblast Tiam1 and OPN expression to the behavior of human breast cancers." (PMID 26821678, 2016). "In addition, by cooperating with ErbB2, a loss of Par3 can inhibit the junction stability of E-cadherin and disrupt cell–cell junctions and cell–cell cohesion through the Tiam1/Rac-GTP pathway, resulting in accelerated metastasis of breast cancer in vivo." (PMID 35875120, 2022). "Moreover, in a large cohort of Her2-positive breast cancer patients, high levels of SRCIN1 expression positively correlates with increased survival in patients with high TIAM1 expression." (PMID 33079227, 2021).
breast cancer (continued). "Given our previous findings demonstrating that DVL-1 plays a critical role in regulating a TIAM1-Rac1 signaling axis in MDA-MB-231 cells, and endogenous DVL-3 co-precipitates with SIRT1 in breast cancer cells, we were interested in exploring these two family members in particular." (PMID 30479694, 2018). "We therefore investigated the hypothesis that the Tiam1-OPN pathway in mammary fibroblasts influences the invasive and metastatic behavior of breast cancers." (PMID 26821678, 2016). "Multivariate survival analysis showed that Tiam1 expression level was a significantly and independent prognostic factor along with tumor stage in breast cancer, but not HER2 expression." (PMID 27562113, 2016). "In addition, a total of 283 breast tissue samples, including 153 breast cancer tissues, 67 ductal carcinoma in situ (DCIS) and 63 adjacent non-tumor breast tissues, were analyzed by immunohistochemical (IHC) staining of the Tiam1 protein." (PMID 27562113, 2016). "Inspired by these findings, we performed IHC staining of Tiam1 protein in 153 breast cancer samples, 67 DCIS and 63 adjacent non-tumor breast tissues." (PMID 27562113, 2016). "We also observed that Tiam1 protein is frequently overexpressed both in breast cancer and DCIS specimens, at significantly higher levels than normal breast tissues." (PMID 27562113, 2016). "Several of the fused genes are also recurrently broken in a substantial proportion of breast cancers, as judged by copy number steps in array-CGH of 1000 breast tumours: around 10% have breaks in ERBB2, BCAS3 and SKAP1, while COL14A1, TIAM1, USP32, TAOK1 are broken in around 4%." (PMID 23260012, 2012). "Although we observed a striking, positive correlation between Tiam1 expression and cell motility in the panel of breast cancer cell lines, we did not observe a correlation between Tiam1 expression and overall levels of Rac activity." (PMID 20819206, 2010). "In mice, Tiam1 expression has been shown to be necessary for Neu-induced, but not Myc-induced, mammary tumor formation." (PMID 20819206, 2010). "Although a positive correlation has been observed between Tiam1 expression and tumor grade in a variety of human malignancies, including breast, its role in breast cancer cells has not yet been examined." (PMID 20819206, 2010). "Therefore, in breast cancer tissues, Trio levels, but not Tiam1 or Vav1, were high and correlated with a poor outcome." (PMID 32322580, 2020). "Most importantly, there are several genes that can distinguish the four breast cancer subtype as specific therapeutic targets for each subtype, including EFCAB2 for luminal A, ATG16L2 for luminal B, C1QTNF6 and NDUFS6 for HER2+, as well as CHERP, TIAM1, and GABRP for TNBC." (PMID 28245581, 2017). "Importantly, high Tiam1 expression also emerged as a significant independent prognostic factor for DFS (HR: 1.470, 95 % CI: 1.056–2.047, P = 0.022) and 10-year OS (HR: 1.549, 95 % CI: 1.112–2.157, P = 0.010) in patients with breast cancer." (PMID 27562113, 2016). "Interestingly, the strongly positive rate of Tiam1 expression was 47.3 % (53/112) in breast cancers with HER2 negative expression, but only 29.3 % (12/41) in case with HER2 positive expression (P = 0.046)." (PMID 27562113, 2016). "Study of larger sample size will be required to fully explore whether the Tiam1-OPN expression patterns we have observed are limited to the stroma around particular breast cancer subsets, or whether this is a general characteristic across multiple breast cancer subsets." (PMID 26821678, 2016). "Therefore, in this study, a total of 153 breast cancer samples, 67 DCIS and 63 adjacent non-tumor breast tissues were evaluated for the expression of Tiam1 by immunohistochemical (IHC) staining." (PMID 27562113, 2016).
colon carcinoma (24 papers, 2006 to 2024). "Thus, TIAM1 expression is negatively associated with colon cancer progression, consistent with our previous finding that TIAM1 antagonized progression of intestinal tumors in ApcMin/+ mice." (PMID 28416184, 2017). "As reported by other researchers, increased Tiam1 protein levels were also correlated with the invasive and metastatic growth of some human breast and colon tumors." (PMID 35875120, 2022). "In the GCSC database, the methylation levels of FGF8, NOG, TCF15, TWIST1, TBX5, SIX2, and TIAM1 are higher in colon cancer." (PMID 34526059, 2021). "Conversely, Tiam1 knockdown inhibits cell growth and invasive properties of the human colon cancer SW480 cell line in vitro, and reduces the growth of subcutaneous xenograft and the development of metastasis after intracaecal orthotopic xenograft in nude mice." (PMID 32178475, 2020). "Much study has reported the ceRNA of circRNAs, for example, circRNA-ACAP2 targets miR-21-5p to regulate the expression of Tiam1 and further modulated colon cancer progression." (PMID 31096819, 2019). "miR-22 expression inhibits cell migration and invasion via targeting transcription factor Sp1, while it suppresses colon cancer cell migration and invasion by inhibiting the expression of T-cell lymphoma invasion and metastasis 1 (TIAM1)." (PMID 25938468, 2015). "For example, miR-21 and miR-31 facilitate invasion and metastasis of colon carcinoma cells by suppressing the same target TIAM1 in TGF-β signaling pathway." (PMID 25406666, 2014). "The upregulation of miR-31 is consistent with its ability to induce migration and tissue invasion of colon cancer cells via targeting of T-cell lymphoma invasion and metastasis 1 (TIAM1)." (PMID 21980368, 2011). "Other guanine nucleotide exchange factors such as Tiam1 have been shown to increase migration and invasion of cancer cells, such as breast and colon cancer." (PMID 21284875, 2011). "The metastatic potential of eight colon tumor cell lines positively correlates with Tiam1 expression, and overexpression of Tiam1 contributes to the metastatic potential of colon cancer cells." (PMID 20819206, 2010). "The methylation of TIAM1 contributed to the metastasis of colon cancer and could be a predictive factor for colon cancer prognosis and a potential target for metastasis inhibition." (PMID 38711144, 2024). "To determine whether this effect could be observed in other cell lines, we used siRNA to deplete Tiam1 in HCT116 colon cancer cells, which, like U2OS cells, have normal centriole numbers." (PMID 33758078, 2021). "The hypermethylation of TIAM1 has a higher survival risk for colon cancer but lacking data in rectal cancer." (PMID 34526059, 2021). "Interestingly, Endophilin stimulates cell migration by binding to RacGEF TIAM1 and potentiates colon cancer metastasis." (PMID 32589750, 2020). "Overexpression of the Rac1-specific GEF, T-cell lymphoma invasion and metastasis 1 (Tiam1), has been reported in highly invasive breast tumours and colon carcinomas, and may contribute to elevated Rac1 signalling in these cancers." (PMID 18826597, 2008). "One study showed that expression of the metastatic exchange factor Tiam1 in colon cancer is inversely related to the methylation status of its promoter; however, TIAM1 gene hypermethylation also occurs in many tumors, and a clear relationship with metastasis could not be observed." (PMID 25248717, 2014). "Our study also highlights a further nuclear role for TIAM1, distinct from TEAD regulation that we previously identified in colon cancer cells." (PMID 34758330, 2021). "In human CRC and in the colon cancer SW480 cell line, CircRNA-ACAP2 and Tiam1 are expressed at a high level." (PMID 32178475, 2020). "In the present study, we investigated the role of TIAM1, a guanine nucleotide exchange factor specific for RAC1, in colon cancer progression." (PMID 28416184, 2017).
colon carcinoma (continued). "Although GOmir only reports T-cell lymphoma invasion and metastasis 1 (TIAM1) as a miRNA-200a target, it was previously validated as a miRNA-31 target in colon cancer cells." (PMID 26379276, 2015). "It is worth noting that, although Tiam1 effects on cellular migration are mediated by Rac1, Tiam1-induced resistance of colon cancer cells to anoikis is independent of the GTPase." (PMID 32178475, 2020). "CircRNA-ACAP2 acted as a miRNA sponge to increase the expression of T lymphoma invasion and metastasis protein 1 (Tiam1) through abolishing the inhibitory function of miR-21-5p for Tiam1 expression, thereby promoting the invasion, migration, and proliferation of SW480 colon cancer cells." (PMID 32213977, 2020). "Furthermore, qRT-PCR analysis for Wnt target genes (including cMyc, Ascl2, Axin2, CD44, CD1, Sox17, Wif1 and Tiam1) did not identify any significant differences between the colonic tumours isolated from both cohorts of mice." (PMID 25881306, 2015).
colorectal cancer (24 papers, 2008 to 2024). A primary or metastatic malignant neoplasm that affects the colon or rectum. "Although TIAM1 is linked to metastasis of colorectal cancer and thus to a more aggressive form of the disease, some studies show improvement in clinical outcome by germline TIAM1 mutations in primary neuroblastoma." (PMID 33692755, 2021). "Although TIAM1 appears to promote cellular migration in colorectal carcinoma, gastric cancer, osteosarcoma, and ovarian cancer, the only TIAM1 germline mutations that have been identified thus far are protective mutations in primary neuroblastomas." (PMID 33692755, 2021). "Tiam1 is a target gene of the Wnt signaling pathway, and the accumulation of Tiam1 transcripts is associated with the invasiveness of colorectal carcinoma cell lines in vitro." (PMID 32178475, 2020). "The present study sheds some light on the mechanism underlying the cross-talk between the Tiam1/Rac1 signalling pathway and the canonical Wnt pathway in colorectal cancer cells." (PMID 18826597, 2008). "For example, SW480 human colorectal carcinoma cell lines with enhanced migratory potential exhibit four- to five-fold increased Tiam1 protein and mRNA expression." (PMID 39493347, 2024). "Tiam1 is downregulated in colorectal cancer and highly expressed in various cancers such as gastric, laryngeal squamous cell carcinoma, and ovarian cancers." (PMID 37027440, 2023). "In colorectal cancer tissues, tumor transcription factor Jun inhibits the transcription of miR-22, and miR-22 targets TIAM1." (PMID 35011220, 2022). "In advanced colorectal cancer, TIAM1 is downregulated and low TIAM1 nuclear levels predict a poor prognosis." (PMID 29652830, 2018). "In keeping with these findings, nuclear TIAM1 is downregulated in advanced colorectal cancer, and low nuclear TIAM1 predicts poor prognosis." (PMID 28416184, 2017). "Another study showed that miR-29b exerts a critical suppressive role on colorectal cancer mediated by the inhibition of Tiam1 and EMT." (PMID 29176935, 2017). "Our previous study in vitro and in nude mice suggested a promotion role of Tiam1 on invasion and metastasis of colorectal cancer (CRC)." (PMID 24069171, 2013). "Our previous study has provided evidence that Tiam1 was closely correlated to metastatic potential of colorectal cancer, and its depletion significantly reduced tumor growth and metastasis ability of CRC cells." (PMID 24069171, 2013). "Our results suggest that endogenous Tiam1 and endogenous β-catenin form a complex in colorectal cancer cells." (PMID 18826597, 2008). "The Rac1-specfic GEF Tiam1 is overexpressed in many colorectal cancers, and is a transcriptional target of the canonical Wnt signalling pathway." (PMID 18826597, 2008). "Moreover, we have more recently shown that TIAM1 present in the nucleus of colorectal cancer (CRC) cells also inhibits migration." (PMID 37748077, 2023). "However, Tiam1 was identified as a critical antagonist of colorectal cancer progression through inhibiting TAZ and YAP." (PMID 36446524, 2023). "identify TIAM1 as a critical antagonist of colorectal cancer progression." (PMID 28416184, 2017). "Our present study provide evidence that the introduction of human Tiam1 gene into the germ-line significantly enhanced the invasion and metastasis of colorectal cancer, while only inconspicuously promotes the development of colorectal tumors which were induced under DMH treatment." (PMID 24069171, 2013). "Tiam1 is a Rac1-specific GEF that is overexpressed in many colorectal cancers." (PMID 18826597, 2008). "Since Tiam1 could influence the association between β-catenin and Rac1, we were prompted to determine whether Tiam1 itself could physically interact with β-catenin in colorectal cancer cells." (PMID 18826597, 2008). "As expected, Tiam1 antibody co-precipitated Rac1 in these colorectal cancer cells." (PMID 18826597, 2008).
colorectal cancer (continued). "Such functions may be conserved, since the drosophila homolog still life/Tiam1 and C. elegans TIAM-1/GEF function during synaptic and, axonal patterning downstream of the netrin receptor UNC-40/DCC (Deleted in Colorectal Cancer), respectively." (PMID 30694177, 2019). "TIAM1 expression was assessed in resected colorectal cancer (CRC) tissues from 300 patients who did or did not respond to chemotherapy." (PMID 30890693, 2019). "Moreover, miR-22 suppressed EMT process and cancer distant metastasis by directly targeting TIAM1 (T-cell lymphoma invasion and metastasis 1) and SIRT1 in colorectal cancer and renal cell carcinoma, respectively." (PMID 29434190, 2018). "Importantly, we also found that nuclear TIAM1 levels were increased in advanced-stage NSCLC human tumors and correlated with poor survival of NSCLC patients, again in contrast to what we have previously observed in colorectal cancer." (PMID 37748077, 2023).